EIF3I (eukaryotic translation initiation factor 3 subunit I)
Diseases named in the same sentence as EIF3I in open-access papers (continued):
Sharing a sentence is not in itself a finding about the gene and the disease.
cancer (14 papers, 2013 to 2025). A tumor composed of atypical neoplastic, often pleomorphic cells that invade other tissues. "For instance, it has been indicated that the changed expression of translation initiation factors, including eIF3i, is associated with cancer cell survival and metastasis." (PMID 39891297, 2025). "It has been shown that eIF3i expression level changes significantly between cancer tissues and surrounding normal tissues." (PMID 39891297, 2025). "Proto-oncogenic EIF3H and EIF3I likely regulate the protein level of downstream factors to facilitate the developmental process of cancer." (PMID 35040374, 2022). "Gene therapy model suggested that the growth and metastasis of cancer cells were suppressed by eIF3i shRNA." (PMID 28193911, 2017). "Overexpression of eIF3i has been found in several types of human cancers, including human colon adenocarcinoma and adenoma, human hepatocelluar carcinoma, head and neck squamous cell carcinomas, breast cancer, cervical cancer and metastatic melanoma." (PMID 28193911, 2017). "We also performed siRNA target for EIF3I to investigate its role in regulation of cancer cell proliferation." (PMID 27340783, 2016). "In addition to RPL11, our study highlights several other ribosomal proteins that have been implicated in cancer progression, such as Ribosomal Protein S4 X (RPS4X) and eukaryotic translation initiation factor 3 subunit i (eIF3i)." (PMID 39891297, 2025). "eIF3i expression is also significantly increased by ~5 fold in cancer compared with their matched normal tissues, consistent with the previous finding, Interestingly, the expression of both eIF3b and eIF3g did not change significantly between cancer and normal tissues." (PMID 39413959, 2024). "Importantly, studies indicated that eIF3i is a proto-oncogene, and its expression has been proven to be upregulated in a series of cancers." (PMID 35433477, 2022). "Levels of nine eIF3 subunits involving eIF3A, eIF3B, eIF3C, eIF3D, eIF3E, eIF3H, eIF3I, eIF3J, and eIF3M were significantly increased in cancer tissues, whereas the eIF3L expression level in tumours was independently decreased than that of normal tissues (p < 0.05)." (PMID 31885740, 2019). "Given that eIF3i is also critical for the proliferation and survival of cancer cells, and that eIF3i is required for the translational activation of VEGF-A, these findings suggested eIF3i could be an important target for cancer therapy." (PMID 28193911, 2017). "EIF3I knock down has modest effect on cancer cells proliferation." (PMID 27340783, 2016). "EIF3I overexpression was observed in many kinds of cancers, including HCC." (PMID 25609201, 2015). "Among these cancer relapse-relevant genes, METTL16, FTO, EIF3D, and EIF3I were good prognostic factors, while TRA2A, HNRNPA2B1, and YTHDC2 were bad ones." (PMID 33273988, 2020). "Except EIF3E and EIF3F found down-regulated and conferred tumor suppressive activity in cancers, majority of EIF3 members including EIF3A, EIF3B, EIF3C, EIF3D, EIF3H, EIF3I and EIF3M were up-regulated and played important roles in tumor progression of multiple cancer types." (PMID 29568350, 2018). "Next, we observed a positive correlation between CLU and EIF3I in HCC samples, supporting the notion that CLU-EIF3I complex may function as a cooperative unit in cancer cells." (PMID 25609201, 2015).
tumor (13 papers, 2015 to 2025). "The expression of eIF3b, eIF3i, eIF3k and eIF3m was increased with the tumor grade, and was associated with poorer overall survival [All Hazard ratio (HR) > 1 and P < 0.05]." (PMID 31171919, 2019). "Next, we sought to study the effects of eIF3i loss-of-function on tumor induced angiogenesis." (PMID 28193911, 2017). "Recent studies have also shown increased expression of eIF3i, another subunit of the eIF3 complex, in various tumours, indicating its involvement in abnormal translation processes." (PMID 38238831, 2024). "In silico, increased gene expression over all four tumor grades was determined for eIF3B, eIF3I, eIF3K and eIF3M." (PMID 33807050, 2021). "Knockdown of eIF3i greatly attenuated the response of endothelial cells to the induction signals from tumor cells." (PMID 28193911, 2017). "Here, we show that eIF3i is critical for selective translational control in endothelial cells during tumor angiogenesis." (PMID 28193911, 2017). "Because tumor angiogenesis shares many common features with embryonic angiogenesis, we sought to test if the expression level of eIF3i is higher in endothelial cells received tumor induction than that in normal control cells." (PMID 28193911, 2017). "Taken together, these results demonstrated that eIF3i expression is induced in endothelial cells by signals promoting embryonic and tumor angiogenesis." (PMID 28193911, 2017). "The fact that eIF3i functions in both tumor cells] and endothelial cell during tumor angiogenesis suggested it can be an attractive therapeutic target." (PMID 28193911, 2017). "In this work, we found that the expression of eIF3i in endothelial cells is significantly up-regulated during embryonic and tumor angiogenesis." (PMID 28193911, 2017). "We show that eIF3i is highly expressed in zebrafish endothelial cells during embryonic angiogenesis and in human umbilical vein endothelial cells (HUVECs) activated by tumor cell derived signals." (PMID 28193911, 2017). "We found that a key translational regulator, eIF3i, is highly expressed in endothelial cells during embryonic and tumor angiogenesis." (PMID 28193911, 2017). "Studies show that eIF3i could aid as a prognostic marker for understanding tumor progression and patient prognosis." (PMID 39891297, 2025). "Additionally, we also showed for the first time a stepwise increase of eIF3I expression over all four tumor grades in protein level." (PMID 33807050, 2021). "However, only eIF3I showed a stepwise increase in protein expression over all four tumor grades; protein expression of the other eIF3-subunits varied between the tumor grades." (PMID 33807050, 2021). "The IDH1 (R132H) mutation had no significant impact on expression status of eIF3I or eIF4H positive tumor cells.Error bars are partly missing because of the low number of samples or similar tissue intensity scores in the immunohistochemical evaluation." (PMID 33807050, 2021). "Consistent with this, it was reported that eIF3i overexpression leads to malignant phenotype of cells and could promote tumor angiogenesis." (PMID 31370342, 2019). "And in cultured HUVECs, eIF3i is significantly induced by hypoxic-tumor-derived signals." (PMID 28193911, 2017). "Therefore, our data suggested that eIF3i is critical for endothelial cell to respond to tumor derived signals." (PMID 28193911, 2017). "Inhibition of eIF3i with liposome delivered eIF3i shRNA efficiently reduces tumor metastasis." (PMID 28193911, 2017). "At 2 days post transplantation, in all the B16 neoplasia, the endothelial cells had penetrated into tumor mass and preferred to form endothelial loops, and finally, these loops assembled into a complex vascular network in eIF3i wildtype or heterozygous embryos." (PMID 28193911, 2017). "Therefore, our work established a selective translational regulatory mechanism during tumor induced angiogenesis and suggested that targeting eIF3i may be applicable for anticancer therapy." (PMID 28193911, 2017).
tumor (continued). "EIF3I plays a crucial role in the initiation of protein synthesis, whereas HDAC1 interacts with the retinoblastoma tumor-suppressor protein to control cell proliferation and differentiation." (PMID 31253147, 2019). "eIF3i is shown to act as a signaling transducer by bind to and activating AKT1 through preventing PP2A-induced AKT1 dephosphorylation in tumor cells." (PMID 28193911, 2017). "In addition, eIF3i could promote tumor angiogenesis through up-regulating VEGFA translation." (PMID 28193911, 2017). "EIF3I can specifically upregulated and interact with phospho-Akt1 (Ser473) to prevent de-phosphorylation by phosphatase PP2A and to sustain oncogenic p-Akt1 activity to facilitate tumor progression." (PMID 29568350, 2018). "Without eIF3i activity, endothelial cells can never migrate toward tumor and tumor angiogenesis was blocked." (PMID 28193911, 2017). "We transplanted B16-RFP cells into the abdominal perivitelline space of 2 days old wildtype or eIF3i mutant zebrafish embryos which also harbor FLK1-EGFP transgene and recorded the induction of endothelial cell migration toward tumor mass in the following 2 days." (PMID 28193911, 2017). "Notably, eIF3I but not eIF4H significantly correlated with tumor size reduction after TMZ treatment." (PMID 37907716, 2023). "However, in eIF3i mutant embryos, no migrations of endothelial cell toward tumor mass were observed throughout this time window." (PMID 28193911, 2017). "In zebrafish angiogenesis model, eIF3i mutant endothelial cells could not respond to induction signals from tumor mass." (PMID 28193911, 2017).
EIF3I also shares sentences with these, for which no sentence is quoted: infection (2 papers); Acute hepatitis (1); cervical cancer (1); colon adenocarcinoma (1); colorectal cancer (1); head and neck squamous cell carcinoma (1); liver diseases (1); lymphoma (1); metastatic melanoma (1); neutropenia (1).